IRS1 (insulin receptor substrate 1)
Diseases named in the same sentence as IRS1 in open-access papers (continued):
Sharing a sentence is not in itself a finding about the gene and the disease.
Insulin resistance (continued). "Another tumor suppressor miR-145 targets insulin receptor substrate-1 (IRS-1) in the insulin-like growth factor pathway and regulates resistin-induced insulin resistance." (PMID 27556491, 2016). "For example, in adipose tissue, both IRS1-dependent and IRS2-dependent signals are impaired in insulin resistance." (PMID 27247938, 2016). "TNF attenuates the insulin-stimulated tyrosine phosphorylation of insulin receptor (IR) and insulin receptor substrate 1 (IRS1) in adipose tissue and muscle, resulting in the occurrence of insulin resistance." (PMID 28025491, 2016). "To evaluate the effect of obesogenic environment on insulin resistance development, we evaluated PTP1B expression and IRS1 and AKT phosphorylation after insulin injection (cava vein)." (PMID 27479001, 2016). "Western blot analysis for p-IRS1Ser302 and IRS1 confirmed the inhibition by C66 and PF00915275 on prednisone-induced insulin resistance in 3T3-L1 cells." (PMID 27841334, 2016). "In obese mice, adipose-derived TNF-α is involved in insulin resistance through the activation of JNK, leading to increased inhibitory serine phosphorylation of insulin receptor substrate-1 (IRS-1pSer) in muscle." (PMID 25617315, 2015). "Infusion of amino acids into humans leads to the activation of S6K1 phosphorylation of IRS-1 Ser1101, a reduction of IRS-1 function and insulin resistance in skeletal muscle." (PMID 26474286, 2015). "This study demonstrated that OA attenuated insulin resistance in HepG2 cells, whose effect is possibly mediated through decreasing the levels of TNF-α and IL-6 and regulating the expression of IRS1 and GLUT4 protein via the NF-κB protein." (PMID 26843885, 2015). "It is well known that JNK can induce IRS-1/2 serine phosphorylation, leading to the suppression of IRS tyrosine phosphorylation and insulin resistance." (PMID 26074875, 2015). "In one hand, leucine activates the mTOR-S6K pathway, which inhibits the insulin receptor substrate 1(IRS1), thus, the over stimulation of this pathway by a high intake of BCAA leads to insulin resistance." (PMID 26217523, 2015). "These alterations lead to decreased tyrosine phosphorylation of insulin receptor substrate (IRS-1 and -2), PI3K activation followed by a decreased serine phosphorylation of Akt and consequently insulin resistance." (PMID 26779183, 2015). "Significantly improved insulin resistance by restoring hepatic FOXO1 nuclear translocation and upregulating gene expression of Akt2, Irs1, Irs2, Pi3kca, Pi3kcg and Pdk1." (PMID 25621503, 2015). "ER stress in hepatocytes and adipocytes contributes to insulin resistance, in part through IRE1-dependent, JNK mediated inhibition of IRS-1 tyrosine phosphorylation, and increased serine phosphorylation." (PMID 25239110, 2014). "The AMPK and IR/IRS-1/PI3-K/Akt pathways are therefore critical signaling pathways in the regulation of glucose metabolism, and appear to contribute to the development of insulin resistance." (PMID 24918297, 2014). "Abnormalities in the signaling pathway, including IRS1, FOXO1 and GSK3β, marked the main characteristics of insulin resistance in Huh7-Pre-miR190b-6 cells." (PMID 24586785, 2014). "The researchers reported that the development of insulin resistance was characterized by increased levels of MAPK, NF-κB, and insulin receptor substrate 1 (IRS-1) serine phosphorylation while Akt expression and insulin contents were markedly reduced." (PMID 24566317, 2014). "Obesity contributes to insulin resistance via ER stress-induced activation of JNK, IRS-1 (Ser307) and the proinflammatory signaling cascades." (PMID 23667647, 2013). "In adipose tissue and liver, however, IL-6 will exert proinflammatory activities, increasing insulin resistance by upregulating SOCS3 (suppressor of cytokine signaling 3) which, in turn, impairs insulin-induced insulin receptor and IRS1 phosphorylation." (PMID 24455420, 2013).
Insulin resistance (continued). "That 2-AA also reduces IRS1 expression suggests that PGC-1β, which is downregulated here, perturbs IRS1 expression, and consequently effects insulin resistance in skeletal muscle." (PMID 24098655, 2013). "SOCS3 induces insulin resistance by directly binding to IRS-1 and promoting the ubiquitination and subsequent degradation of IRS-1." (PMID 24349514, 2013). "In mouse C2C12 myotubes, AMPK activation potentiated insulin action by reducing IRS-1 serine phosphorylation, while reduced muscle AMPK activity has been reported to aggravate muscle insulin resistance following a high-fat diet over 30 weeks." (PMID 23861559, 2013). "S6K1-mediated phosphorylation of insulin receptor substrate 1 (IRS-1) downregulates IIS and thus induces insulin resistance." (PMID 23614736, 2013). "Ang II promotes insulin resistance and inhibits insulin metabolic signalling by activating mTOR and thus promoting S6K1-mediated IRS-1 serine phosphorylation." (PMID 24400038, 2013). "Pretreatment with quercetin and Gelam honey extract improved insulin resistance and insulin content by reducing the expression of MAPK, NF-κB, and IRS-1 serine phosphorylation (ser307) and increasing the expression of Akt significantly." (PMID 24324490, 2013). "Reductions in the phosphorylated forms of insulin receptor (IR), insulin receptor substrate-1 (IRS-1), and expression of the Akt2 gene within adipose tissue and with time fasting are also suggestive of mounting insulin resistance in elephant seal weanlings." (PMID 24198811, 2013). "Thus, obesity might be associated with high levels of IRS1 protein expression whilst there is not insulin resistance." (PMID 23110196, 2012). "On the other hand phosphorylation of JNK will lead to the inhibition of insulin receptor substrate 1 (IRS-1) and ultimately insulin resistance in the host." (PMID 22970372, 2012). "HCV infection promotes insulin resistance, mainly through increased tumor necrosis factor α (TNF-α), which inhibit insulin receptor and IRS-1 (insulin receptor substrate) tyrosine phosphorylation." (PMID 22675572, 2012). "For example, IRS1 gene knockout mice have mild insulin resistance with normoglycemia, while IRS2 gene knockout mice suffer from severe hyperglycemia with insulin resistance and reduction of the β cell mass." (PMID 23346100, 2012). "Phosphorylation of insulin receptor substrate-1 (IRS-1) by JNK leads to the inhibition of insulin signal transduction and contributes to peripheral insulin resistance." (PMID 24278747, 2012). "Activated TNFα inhibits tyrosine phosphorylation of IRS1 and IRS2, and impairs glucose transporter (GLUT)-4 translocation to the cell membrane, leading to insulin resistance and hyperinsulinemia, which can increase glycogenolysis and fatty acid synthesis." (PMID 22701799, 2012). "ERK is one of the IRS-1 kinases which can upregulate serine phosphorylation of IRS-1 following an inhibition of IRS-1 function and eventually leading to insulin resistance." (PMID 22721429, 2012). "It has been reported that serine phosphorylation of insulin receptor substrate-1 (IRS-1) inhibits insulin-stimulated tyrosine phosphorylation of IRS-1, leading to an increase in insulin resistance." (PMID 20182627, 2010). "Serine phosphorylation of IRS-1 disassociates coupling of IRS-1 signal transduction to PI3K and results in insulin resistance." (PMID 19169352, 2009). "In the T2D model, TH mice exhibited more severe hyperglycemia, insulin resistance, and β‐cell dysfunction than TN mice, accompanied by increased hepatic TNF‐α and IL‐6 expression, enhanced lipid accumulation, suppressed IRS‐1 phosphorylation, and enhanced JNK and IKKβ phosphorylation." (PMID 41388732, 2026). "Elevated BCAA levels can activate the mechanistic target of the rapamycin (mTOR)-p70 S6 kinase (p70S6K) pathway, inhibiting insulin receptor substrate-1 (IRS-1) phosphorylation and reducing insulin signaling, which impairs glucose transport and leads to insulin resistance." (PMID 40559421, 2025).
Insulin resistance (continued). "These mediators could inhibit downstream signaling of insulin receptor substrate-1 (IRS-1) by activating serine kinases including JNK and IKK, leading to impaired glucose utilization in peripheral tissues—insulin resistance." (PMID 41293736, 2025). "Additionally, SAMC can reduce inflammatory responses by targeting NF-κB, and improve lipid homeostasis and insulin resistance through regulating AMPK and IRS-1/PI3K/Akt pathways." (PMID 41347177, 2025). "This microenvironment promotes the secretion of cytokines, such as TNF-α and IL-6, which impair insulin signaling by inhibiting the IRS-1/PI3K/Akt pathway, contributing substantially to the systemic insulin resistance observed in the Ob-Veh and HE-Ob-Veh groups." (PMID 41471698, 2025). "Notably, exosomes derived from lipid-dysregulated adipocytes carry miR-1 and miR-133 that target IRS-1 and INSR, thereby exacerbating insulin resistance." (PMID 41438998, 2025). "Insulin resistance arises from chronic nutrient overload, which activates inflammatory pathways including NF-κB and JNK in the liver, muscle, and adipose tissue, thereby impairing insulin signaling through serine phosphorylation of IRS-1." (PMID 40867531, 2025). "TNF-α (tumor necrosis factor-alpha) is a key cytokine that is elevated in both conditions, which is known to inhibit insulin receptor signaling by inducing the serine phosphorylation of insulin receptor substrate-1 (IRS-1), leading to reduced glucose uptake and systemic insulin resistance." (PMID 40142617, 2025). "While previous studies have demonstrated the ameliorative effects of GP on insulin resistance via modulation of NF-κB and GLUT4 in HepG2 cells and regulation of Akt, IRS-1, and GLUT-1 in in 3T3-L1 adipocytes, our study extends these findings in several important ways." (PMID 40869401, 2025). "The mechanism by which TNF‐alpha induces insulin resistance is not fully understood, but one proposed pathway involves the activation of the JNK pathway, leading to serine 307 phosphorylation of insulin receptor substrate‐1 (IRS‐1)." (PMID 40551726, 2025). "Glucose-mediated insulin resistance provides a feedback mechanism sometimes independent of the activation of mTOR and it is due to direct phosphorylation and inhibition of IRS-1 by S6 kinase." (PMID 40277891, 2025). "Furthermore, berberine promotes AKT activation by modulating upstream regulators such as IRS-1 and PI3K, which in turn facilitates downstream signaling and ameliorates insulin resistance." (PMID 41471379, 2025). "Therefore, the inhibition of IRS-1 and GLUT4 due to various factors can result in insulin resistance and disruptions in glucose and lipid homeostasis." (PMID 41011216, 2025). "Additionally, PI3K/AKT, through the dephosphorylation of Insulin Receptor Substrate 1 (IRS1) and Insulin Receptor Substrate 2 (IRS2), also counteracts the development of insulin resistance." (PMID 40427436, 2025). "During the insulin resistance condition, there is a dysregulation in the insulin response signaling pathway, the Protein Kinase B (Akt)/Phosphoinositide 3-kinase (PI3K)/Insulin receptor substrate 1 (IRS-1)." (PMID 41488874, 2025). "Transcriptomic data show that insulin secretion‐related genes (IRS1, PRKCA/PKCα) in cave loaches are significantly downregulated, rather than exhibiting mutations related to insulin resistance." (PMID 41383212, 2025). "For instance, increased levels of BCAAs (valine and alanine) are well-established contributors to insulin resistance through mTORC1 overactivation, which initiates a negative feedback loop that impairs insulin receptor substrate-1 (IRS-1) signaling." (PMID 41373836, 2025). "TNF-α induces insulin resistance through direct negative interference with the insulin signaling pathway, IRS1 phosphorylation, and alteration of adipocyte differentiation and metabolism." (PMID 41226064, 2025).
Insulin resistance (continued). "In metabolic tissues, particularly adipose and skeletal muscle, ROS impair insulin signaling by altering adipokine profiles (decreased adiponectin and increased leptin/resistin) and by inhibiting key signaling molecules like IRS-1 and GLUT4, resulting in systemic insulin resistance." (PMID 41235339, 2025). "Notably, irisin has been shown to enhance PI3K/AKT insulin signaling and reduce the serine phosphorylation of IRS-1 and IRS-2, which are key molecular mechanisms contributing to insulin resistance." (PMID 39769243, 2024). "Previous research has shown that RS could relieve insulin resistance through the Sirt1-p-AMPK-p-AKT and Sirt1-p-IRS-1-p-AKT pathways in adipocytes, thereby promoting glucose uptake through increased membrane accumulation of Glut4." (PMID 38903985, 2024). "Activated TNF-α can elevate plasma FFA levels by promoting lipolysis, inhibit the tyrosine kinase activity of insulin receptors in muscle tissue, and suppress IRS-1 phosphorylation and GLUT4 gene expression, resulting in insulin resistance and also stimulate IL-6 production." (PMID 40302954, 2024). "In DKO male mice, hepatic ERα knockout did not further aggravate glucose intolerance and insulin resistance, which suggests that IRS1 and 2 are required for ERα ligand-independent effect." (PMID 38649684, 2024). "For example, mice lacking insulin receptor substrate 1, despite exhibiting persistent insulin resistance, demonstrated reduced age-related markers of senescence and increased longevity." (PMID 39872311, 2024). "The site of betaine’s action in normalizing insulin resistance appears to be at the level of tyrosine phosphorylation of IRS1, but not at the phosphorylation of insulin receptor nor at the amount of insulin receptor." (PMID 39119463, 2024). "Similarly, the expression of c-miR-126 has also been shown to be altered with exercise and concomitantly a potential biomarker for type-2 diabetes due to its interference with insulin signaling by targeting IRS1 and IRS2, resulting in insulin resistance." (PMID 38903909, 2024). "Hepatic ablation of IRS1 and IRS2 leads to insulin resistance and hyperglycemia in mice." (PMID 38649684, 2024). "In addition, a study showed that HFD-induced mice and PA-induced HepG2 cells treated with quercetin saw a enhancement alleviation of insulin resistance via the IRS-1/AKT/FoxO1 pathway, and stimulated expressions of p-IRS1, p-AKT and GLUT4 in liver." (PMID 38799166, 2024). "Modulating insulin signaling pathways through agents that enhance IRS-1 and IRS-2 function or inhibit their aberrant phosphorylation could improve glucose uptake and reduce insulin resistance." (PMID 39519193, 2024). "Insulin receptor substrate 1 (IRS1), protein kinase B (AKT), and ERK are the key components of the insulin signaling pathway; impaired IRS1 signaling leads to decreased activation of AKT and subsequent dysregulation of ERK involved in insulin resistance and metabolic dysfunction." (PMID 39626951, 2024). "Moreover, Aβ accumulation stimulates serine phosphorylation of insulin receptor substrate-1 (IRS-1), consequently impairing insulin signaling, releasing inflammatory molecules, and contributing to brain insulin resistance." (PMID 37511061, 2023). "In the context of obesity and type 2 diabetes, metabolic and inflammatory stress increase the activities of JNK and ERK in insulin target tissues, and these kinases induce serine phosphorylation of IRS1 or IRS2, whereas uncontrolled IRS serine phosphorylation promotes insulin resistance." (PMID 37108143, 2023). "It has been reported that mice with Irs2 gene knockout exhibited selective insulin resistance, while mice lacking Irs1 or Irs1 and Irs2 developed total insulin resistance." (PMID 36982617, 2023). "Serine phosphorylation of insulin receptor substrate-1 (IRS-1) especially inhibits insulin signal transduction, which might contribute to insulin resistance." (PMID 37432173, 2023).
Insulin resistance (continued). "ROS is known to play a part in activation of intracellular stress kinases and inhibition of IRS-1, thus potentially influencing insulin signaling and to promote via GLUT-4 translocation and down streaming of AKT resulting in insulin resistance, obesity and diabetes mellitus." (PMID 37089941, 2023). "Mitochondrial dysfunction and subsequent excess ROS production promote insulin resistance by activating c-Jun N-terminal kinases (JNK) and NLR family pyrin domain containing 3 (NLRP3) inflammasome which leads to the deactivation of the IRS1/PI3K/AKT pathway and the progression of insulin resistance." (PMID 37106780, 2023). "Combinational usage showed an increase in inflammasome-related genes and enzymes, resulting in reduced IRS1 signaling and, subsequently, promotion in insulin resistance despite the drugs not achieving the same result during individual exposure." (PMID 37047241, 2023). "Recent studies have shown that paeoniflorin can improve insulin resistance and protect β cells, by inhibiting the activation of Rho kinase (ROCK) and serine phosphorylation of INSR substrate (IRS)-1, and promoting AKT and glycogen synthase kinase (GSK)-3β phosphorylation." (PMID 37324475, 2023). "In addition, for circFAT3 KD, genes related to insulin signaling and insulin resistance (PPARGC1A, SLC27A2, PPARGC1B, PRKCQ, GYS1, and IRS1) were the top hits." (PMID 36840844, 2023). "In addition, pro-inflammatory markers promote insulin resistance by reducing GLUT4 content, insulin receptor and IRS1 gene expression." (PMID 38027196, 2023). "Therefore, the current study suggests that miR-183-5p upregulated by SFA or obesity contributes to the development of hepatic insulin resistance and T2DM by suppressing IRS-1." (PMID 35328400, 2022). "In addition, the 14-3-3 protein has been reported to inhibit the expression of insulin receptor substrate 1 (IRS1), leading to insulin resistance, although the exact mechanism needs to be further explored." (PMID 35712251, 2022). "However, for the validated genes, IRS-1 was overexpressed and TNFα was downregulated post-RYGB in both low and high insulin resistance." (PMID 36432612, 2022). "A recent study demonstrated that EA improved the insulin resistance score compared with the control group in PCOS patients, and the protective effect of EA might be through an upregulation of the IRS-1/PI3K/GLUT4 signaling pathway." (PMID 36353235, 2022). "Naringin not only had improved insulin resistance and increased the gene expression of the antioxidant enzymes (SOD1 and CAT), mTOR, and PGC-1α, but the expressions of IRS-1 and GLUT4 proteins were also increased, which led to increases in the glucose uptake and the glycogen levels." (PMID 36235772, 2022). "Furthermore, these two phytochemicals attenuated insulin resistance via increasing the insulin sensitivity, Akt, and glycan synthse kinase-3 (GSK3) β and decreasing insulin receptor substrate 1 (IRS-1) phosphorylation." (PMID 36028892, 2022). "Insulin resistance and hyperinsulinemia stimulate the release of insulin-like growth factor 1 (IGF-1) and IRS-1, mediating signals for cell proliferation and inhibition of apoptosis and might contribute to the development of HCC." (PMID 36612019, 2022). "Since leucine upregulates mTORC1, subsequently inducing the suppression of insulin signal transduction by phosphorylation of insulin receptor substrate-1 (IRS-1), leucine supplementation might worsen insulin resistance." (PMID 36235570, 2022). "The treatment of PPH was also found to regulate the insulin signaling in our study, which is consistent with a previous study reporting that the intragastric administration of PPH upregulated the gene expressions of IRS1 and IRS2 in the liver of diabetic mice, and reduced insulin resistance." (PMID 36011893, 2022).